RBM47 (RNA binding motif protein 47)
Diseases named in the same sentence as RBM47 in open-access papers (continued):
Sharing a sentence is not in itself a finding about the gene and the disease.
thyroid cancer (5 papers, 2022 to 2025). "In summary, SNHG5 is universally underexpressed in thyroid cancer and exerts tumor-suppressive effects through the RBM47/USP21/FOXO3 pathway and miR-510-5p-related mechanisms." (PMID 41234719, 2025). "Research has shown that RBM47 plays an important role in the progression of various cancers, including colorectal cancer, thyroid cancer, hepatocellular carcinoma, and nasopharyngeal cancer." (PMID 39757245, 2025). "Functional experiments demonstrated that high RBM47 expression inhibits thyroid cancer cell proliferation by regulating the LC3 II/LC3 I ratio in the autophagy flux." (PMID 41234719, 2025). "In this study, RBM47 was significantly downregulated in thyroid carcinoma, and overexpression of RBM47 inhibited proliferation and activated autophagy in PTC cells." (PMID 35338124, 2022). "However, the expression level and biological function of RBM47 in thyroid carcinoma remain unclear." (PMID 35338124, 2022).
Hypertension (4 papers, 2020 to 2023). The presence of chronic increased pressure in the systemic arterial system. "Another study aimed at finding rare and common variants associated with hypertension identified 31 novel genetic regions—rare missense variants in RBM47, COL21A1, and RRAS." (PMID 36902588, 2023). "ULK4 and FHIT genes have 17 and 10 EH-associated SNPs, respectively, while FNDC3B, FHIT, NPPC-DIS3L2, GLI2, and RBM47 include SNPs that have a ≥4 log-p value association with hypertension in the studied cohort." (PMID 35629146, 2022). "They identified 30 new blood pressure- or hypertension-associated genetic regions in the general population, including 3 rare missense variants in RBM47, COL21A1 and RRAS with larger effects than common variants." (PMID 33240327, 2020). "In addition, we identified 21 common genes that are shared between the GWAS and text mining analyses; of these, FNDC3B, FHIT, NPPC-DIS3L2, GLI2, and RBM47 genes are the most highly associated with hypertension." (PMID 35629146, 2022). "Rare putative functional hypertension-associated variants in the RBM47 gene were discovered." (PMID 35629146, 2022). "Additionally, RBM47 was identified to be associated with blood pressure or hypertension." (PMID 35597927, 2022).
atherosclerosis (3 papers, 2020 to 2025). A disease characterized by the build-up of fatty material and calcium deposition in the arterial wall resulting in partial or complete occlusion of the arterial lumen. "RBM47, HCK, CD53, TYROBP, and HAVCR2 were identified as common hub genes, which were validated to be upregulated in advanced atherosclerotic plaques, to well distinguish CAD patients from non-CAD people and to regulate immune cell function-related mechanisms in advanced atherosclerosis." (PMID 33519905, 2020).
lung adenocarcinoma (3 papers, 2020 to 2026). A carcinoma that arises from the lung and is characterized by the presence of malignant glandular epithelial cells. "To further investigate the potential link between RBM47-ISGylation deficiency and lung tumorigenesis, we utilized the urethane-induced lung adenocarcinoma mouse model, which causes tumors primarily through Kras mutations." (PMID 38036512, 2023). "As a tumor suppressor gene, RBM47 inhibits tumor cell growth through the inhibition of Nrf2 activity in lung adenocarcinoma, and RBM47 knockdown enhanced tumor formation and metastasis in a xenograft mouse model." (PMID 33229623, 2020). "Notably, Lewis lung carcinoma is a spontaneous adenocarcinoma of the lung originating in C57BL/6 mice, suggesting a potential link between RBM47-ISGylation deficiency and lung tumorigenesis in mice." (PMID 38036512, 2023).
adenoma (2 papers, 2023 to 2025). A neoplasm arising from the epithelium. "During adenoma to carcinoma progression the RBM47 promoter becomes increasingly hypermethylated, suggesting that the initial downregulation of RBM47, at least in part, due to the down-regulation of FOXA1 is epigenetically fixed." (PMID 41335176, 2025). "In silico data sets from the National Center for Biotechnology Information (NCBI) Gene Expression Omnibus (GEO) further revealed that RBM47 was downregulated in both human adenocarcinoma and adenoma tissue compared with paired uninvolved tissue." (PMID 37014710, 2023). "Therefore, the following scenario appears likely: During the initiation of early adenomas, the expression of FOXA1 and consequently RBM47 is decreased." (PMID 41335176, 2025).
colitis (2 papers, 2019 to 2023). Inflammation of the colon. "Alternatively, we considered the enhanced recovery and augmented antioxidative response with DSS injury in Rbm47-IKO mice might mitigate colitis-associated cancer and thus reduce the tumor burden." (PMID 37014710, 2023). "Rbm47-IKO mice adapted to radiation injury and were protected against chemical-induced colitis, with Rbm47-IKO intestine showing upregulation of antioxidant and Wnt signaling pathways as well as stem cell and developmental genes." (PMID 37014710, 2023). "Rbm47-IKO mice exhibit augmented antioxidative capacity, which confers protection from inflammation-associated and oxidative injury in colitis-associated carcinogenesis." (PMID 37014710, 2023). "In addition, we find that Rbm47-IKO mice exhibit adaptive responses to both radiation-induced injury and experimental colitis induced by DSS exposure, along with reduced colitis-associated tumorigenesis." (PMID 37014710, 2023). "Rbm47-IKO mice exhibit protection against dextran sodium sulfate–induced colitis." (PMID 37014710, 2023). "Importantly, Rbm47-overexpressing B cells suppress inflammation in mice suffering from colitis by inducing Tregs." (PMID 29844590, 2019). "Moreover, B cells in the mLNs of mice with DSS-induced colitis had a markedly lower expression level of Rbm47 and IL-10." (PMID 29844590, 2019).
diabetes (2 papers, 2014 to 2025). "Ontological classification demonstrates that these 14 genes are associated with diabetes (ALMS1P; RAET1L; GYS1; RBM47; EFR3B), cancer (RPL27A; SPAM1; PTCH1; ZNF277; USP35; CDC86), or metabolism (C3orf15; AOC2; GOT1)." (PMID 24885560, 2014).
melanoma (2 papers, 2019 to 2021). A malignant, usually aggressive tumor composed of atypical, neoplastic melanocytes. "Jiang and Liu reported that miR-25 target the RNA-binding motif protein 47 (RBM47) and activated the PI3K/Akt/mTOR signaling pathway in melanoma cells." (PMID 31370278, 2019).
neuroendocrine pancreatic tumors (2 papers, 2021 to 2023). "Downregulation of RBM47 is observed with altered promoter methylation in neuroendocrine pancreatic tumors, suggesting yet another mechanism underlying a loss-of-function role in tumorigenesis." (PMID 37014710, 2023). "The hypermethylation of the promoter of RBM47 had been detected in nonfunctioning pancreatic neuroendocrine tumors." (PMID 34182539, 2021).
polyposis (2 papers, 2023 to 2025). "Recently, intestinal epithelial-specific deletion of Rbm47 was shown to cause polyposis in aged mice, whereas the same mice were protected against colitis-associated cancer, suggesting that the role of RBM47 in carcinogenesis may depend on the context." (PMID 41335176, 2025). "Rbm47-IKO mice exhibit spontaneous polyposis and increased polyp burden in compound Rbm47-IKO ApcMin/+ background." (PMID 37014710, 2023). "By contrast, aged Rbm47-IKO mice developed spontaneous polyposis, and Rbm47-IKOApcMin/+ mice manifested an increased intestinal polyp burden." (PMID 37014710, 2023). "In line with the increased growth and proliferation phenotypes, we find that Rbm47-IKO mice exhibit spontaneous polyposis with aging and an exaggerated polyposis phenotype in the ApcMin/+ background." (PMID 37014710, 2023). "However, attenuated inflammatory and oxidative injury may be less relevant than upregulation of cell proliferation, particularly in the setting of spontaneous polyposis in Rbm47-IKO mice." (PMID 37014710, 2023). "We observed upregulation of the IL-33/AREG axis in Rbm47-IKO mice, a pathway previously shown to promote polyposis in ApcMin/+ mice." (PMID 37014710, 2023). "Taken together with the current findings showing increased IL-33 and AREG expression in Rbm47-IKO mice, we propose that these adaptations might plausibly protect against intestinal injury and inflammation-associated tumorigenesis while promoting spontaneous polyposis." (PMID 37014710, 2023).
renal carcinoma (2 papers, 2023 to 2025). A carcinoma arising from the epithelium of the renal parenchyma or the renal pelvis. "The results represented that knockdown RBM47 reduced e-cadherin and facilitated snail and vimentin in renal cancer cells while RBM47 overexpression achieved the opposite results." (PMID 37962768, 2023). "Then, we investigated the prognostic role of RBM47 in renal cell carcinoma due to the reduced expression of RBM47 in renal cancer." (PMID 37962768, 2023). "Subsequently, we verified the expression and role of RBM47 in renal cancer cells, as it can serve as a prognostic marker for renal cancer patients." (PMID 37962768, 2023). "RBM47 expression in renal cancer cell lines was reduced significantly when compared to normal renal tubular epithelial cells." (PMID 37962768, 2023). "Here, we investigated the clinical pathological characteristics and patient survival rate of RBM47 in ccRCC, as well as its function role in renal cancer cells." (PMID 37962768, 2023). "The possible mechanism of RBM47 in renal cancer was verified by gene function prediction and in vitro experiments." (PMID 37962768, 2023). "The results showed the mRNA and the protein levels of RBM47 were down-expressed in renal cancer cells." (PMID 37962768, 2023). "Mechanically, RBM47 could directly modify RNA stability of e-cadherin, but indirectly regulate snail, vimentin in renal cancer cells." (PMID 37962768, 2023). "RBM47 overexpression could repress the migration, invasion activity, and proliferation capacity of renal cancer cells, while RBM47 inhibition could promote the development of the malignant features through EMT signaling by RNA stability modification." (PMID 37962768, 2023). "Knockdown RBM47 promoted the proliferation ability of renal cancer cells." (PMID 37962768, 2023). "We found that RBM47 overexpression inhibited EMT of renal cancer cells." (PMID 37962768, 2023). "The results showed that RBM47 was downregulated in renal cancers when compared with control groups." (PMID 37962768, 2023). "Furthermore, RBM47 overexpression inhibited the progression of ccRCC, whereas RBM47 knockdown enhanced the proliferation and malignant features of renal cancer cells." (PMID 37962768, 2023). "The results showed a decrease in the expression of RBM47 in renal cancer tissues, indicating that it may have a certain inhibitory effect on renal cell carcinoma." (PMID 37962768, 2023). "The results showed that RBM47 can serve as a prognostic marker for renal cancer patients." (PMID 37962768, 2023). "Next, we studied the invasion and migration role of RBM47 on renal cancer cells by plasmid transfection, as it could inhibit the growth of renal cancer." (PMID 37962768, 2023). "And, we investigated how RBM47 regulated EMT signaling in renal cancer cell lines." (PMID 37962768, 2023). "Subsequently, we verified the role of RBM47 in renal cancer cell lines." (PMID 37962768, 2023). "RBM47 overexpression plasmid transfection could inhibit renal cancer cell wound-healing ability." (PMID 37962768, 2023). "At last, we verified the relationship of RBM47 and EMT pathway in renal cancer cells by qRT-PCR and WB." (PMID 37962768, 2023). "RNA binding motif protein 47 (RBM47) has been proven to have anti-tumor effects on many cancers, but its effect is not yet clear in renal cancer." (PMID 37962768, 2023). "The same results were verified in renal cancer tissues, with a positive correlation between RBM47 and CDH1(e-cadherin), a negative correlation between RBM47 and TGF-β, snail, vimentin by qRT-PCR, and western blot (WB)." (PMID 37962768, 2023). "RBM47 can directly modify the RNA stability of e-cadherin, indicating that it may affect the EMT characteristics of renal cancer cells and serve as a marker of renal cell carcinoma." (PMID 37962768, 2023). "High RBM47 expression indicated good progression, and could inhibit EMT of renal cancer cells." (PMID 37962768, 2023).
renal cell carcinoma (2 papers, 2023). "In order to validate the expression pattern of RBM47 in renal cell carcinoma, we first evaluate the expression of RBM47 in the TCGA-KIRC database." (PMID 37660095, 2023). "The result showed that RBM47 was downregulated in renal cell carcinoma tissues compared with normal tissues." (PMID 37660095, 2023). "Moreover, the overexpression of RBM47 and sunitinib had a synergistic anticancer effect on renal cell carcinoma cells." (PMID 37660095, 2023). "Subsequently, we investigated the signaling pathways that RBM47 may be involved in as it can inhibit the malignant features of renal cell carcinoma." (PMID 37962768, 2023). "The expression of RBM47 was downregulated in renal cell carcinoma tissues and cells." (PMID 37962768, 2023). "Previous studies have not reported the role of RBM47 in renal cell carcinoma, and this study report the role of RBM47 in ccRCC for the first time." (PMID 37962768, 2023).
cholangiocarcinoma (1 paper, 2023). A carcinoma that arises from the intrahepatic biliary tree (intrahepatic cholangiocarcinoma) or from the junction, or adjacent to the junction, of the right and left hepatic ducts (hilar cholangiocarcinoma). "As TGF-β signaling could induce EMT in cholangiocarcinoma and hepatic stellate cells, we incorporate the functional of RBM47 on EMT signaling." (PMID 37962768, 2023).
colon adenocarcinoma (1 paper, 2025). "By investigating the cancer genome atlas (TCGA) dataset of colon adenocarcinoma (COAD) patients, we found RBM47 was significantly downregulated in tumor samples compared with adjacent normal samples." (PMID 40695891, 2025).
colorectal tumors (1 paper, 2025). "Since our results implied that the down-regulation of FOXA1 and RBM47 expression promotes tumor progression, FOXA1 and RBM47 expression in different stages of colorectal tumors was analyzed." (PMID 41335176, 2025). "Indeed, FOXA1 and RBM47 expression progressively decreased from stage 1 to stage 4 colorectal tumors in the majority of analyzed CRC patient cohorts." (PMID 41335176, 2025).
glioma (1 paper, 2025). A benign or malignant brain and spinal cord tumor that arises from glial cells (astrocytes, oligodendrocytes, ependymal cells). "Increased RBM47 expression is associated with poor prognosis in patients with glioma, serving as an independent predictor of overall survival." (PMID 39757245, 2025). "Our results suggest that RBM47 reshapes the immune microenvironment of gliomas by modulating M2 macrophages, thereby affecting the prognosis of patients with glioma, making it a potential immunotherapy target." (PMID 39757245, 2025). "In conclusion, this multi-dataset study, coupled with immunohistochemical analyses, revealed that RBM47 is highly expressed in gliomas and is correlated with increasing malignancy." (PMID 39757245, 2025). "Subsequently, we immunofluorescently stained tumor samples and found a co-expression pattern of CD163 and RBM47 within the glioma samples, suggesting a potential interaction between the two." (PMID 39757245, 2025). "We conducted immunohistochemistry on glioma paraffin sections and demonstrated that RBM47 is highly expressed in gliomas and is positively correlated with the degree of tumor malignancy." (PMID 39757245, 2025). "We employed bioinformatics analyses to investigate the role of RBM47 in the immune process of gliomas." (PMID 39757245, 2025). "The role of RBM47, an RNA-binding protein, in shaping the immune landscape of gliomas and tumor immune responses is yet to be fully studied." (PMID 39757245, 2025). "We observed significantly higher RBM47 expression levels in glioma tissue compared with those in normal tissues, as evidenced by GSE4290 data." (PMID 39757245, 2025). "Accordingly, RBM47 likely regulates the immune microenvironment in gliomas by modulating M2 macrophages." (PMID 39757245, 2025). "We validated the differences in RBM47 protein expression levels across gliomas of different grades and normal tissues through immunohistochemistry (IHC)." (PMID 39757245, 2025). "We investigated the relationship between RBM47 expression and several clinical features in patients with glioma using RNA-seq data from TCGA and CGGA." (PMID 39757245, 2025). "The expression of RBM47 in gliomas was higher than that in normal tissues and was positively correlated with the World Health Organization tumor grade." (PMID 39757245, 2025). "In the CGGA database, RBM47 expression demonstrated an upward trend, correlating with increases in glioma grade, consistent with the results of GSE4290 data." (PMID 39757245, 2025). "To gain further insights into the function of RBM47 in the immune microenvironment of gliomas, we explored the relationship between RBM47 and the inflammatory response." (PMID 39757245, 2025). "Comparable findings were replicated in the TCGA database, reinforcing the notion that RBM47 plays a pivotal role in modulating immunity, inflammation, immune-mediated disorders, as well as the intricate glioma microenvironment." (PMID 39757245, 2025). "Therefore, a comprehensive investigation into the immunomodulatory roles of RBM47 in gliomas was conducted, leveraging gene expression data from multi-omic datasets." (PMID 39757245, 2025). "We also validated the co-expression of CD163 and RBM47 in glioma samples using immunofluorescence." (PMID 39757245, 2025). "RBM47 overexpression is an independent predictor of poor prognosis in patients with glioma." (PMID 39757245, 2025). "However, our single-cell sequencing data analysis revealed that RBM47 was predominantly expressed in M2 macrophages and was partially expressed in glioma cells." (PMID 39757245, 2025). "Therefore, we propose RBM47 as a potential immunotherapeutic target and prognostic biomarker for gliomas, though further mechanistic validation is needed." (PMID 39757245, 2025).
glioma (continued). "By co-culturing glioma cell lines with induced M2 macrophages and subsequently subjecting the macrophages to RBM47 knockdown, we can observe the proliferation, invasion, and migration abilities of tumor cells, which will help to understand the function of RBM47." (PMID 39757245, 2025). "However, the role of RBM47 in glioma and its impact on tumor immune responses has yet to be thoroughly investigated." (PMID 39757245, 2025). "This means that RBM47 may be involved in the malignant progression of gliomas." (PMID 39757245, 2025). "Therefore, RBM47 plays a vital role in the immune microenvironment of gliomas and may be a potential immunotherapy target." (PMID 39757245, 2025). "Therefore, RBM47 may serve as a potential prognostic factor in patients with glioma." (PMID 39757245, 2025). "In addition, RBM47 was enriched in wild-type IDH and 1p/19q co-deletion glioma samples, subtypes representing gliomas with poor prognosis and high malignancy." (PMID 39757245, 2025). "In addition, RBM47 expression was notably higher in isocitrate dehydrogenase (IDH)-wild-type glioma samples, those without 1p/19q co-deletion, and those devoid of methylguanine-DNA methyltransferase promoter methylation." (PMID 39757245, 2025).
intestinal polyposis (1 paper, 2023). "Based on those observations, we asked if epithelial Rbm47 deletion would function as a dominant driver of intestinal polyposis in the setting of adenomatous polyposis coli (Apc) loss, a hypothesis we examined by generating a line of Rbm47-IKO mice in the ApcMin/+ background." (PMID 37014710, 2023).
intestinal tumors (1 paper, 2023). "The downregulation of RBM47 could regulate the occurrence of intestinal tumors by regulating proliferative inflammation and oxidative response pathways." (PMID 37962768, 2023).